BCL2A1 (BCL2 related protein A1)
Diseases named in the same sentence as BCL2A1 in open-access papers (continued):
Sharing a sentence is not in itself a finding about the gene and the disease.
ovarian carcinoma (continued). "By quantifying the band intensities of BCL2A1, we noted a 2.7-fold increase in BCL2A1 in metastatic ovarian cancer cells isolated from lavage/ascites compared with those isolated from primary ovarian tumors." (PMID 34572804, 2021). "This indicates that BCL2A1 enhances the viability of ovarian cancer cells under hypoxic conditions." (PMID 34572804, 2021). "We demonstrated that BCL2A1 was induced not only by hypoxia but also other physiological stresses through NF-κB signaling and then was gradually reduced by the ubiquitin-proteasome pathway in ascites-derived ovarian cancer cells." (PMID 34572804, 2021). "Similarly, herein, a BCL2A1 promoter-luciferase assay, overexpression, depletion of RELA by RNAi, or inhibition by pharmaceutical approaches in ovarian cancer cells suggest that NF-ĸB signaling is the upstream regulator of BCL2A1 transcriptional activity." (PMID 34572804, 2021). "Hence, targeting BCL2A1 is likely a potential therapeutic approach in eradicating peritoneal metastases of ovarian cancer." (PMID 34572804, 2021). "In this study, our findings demonstrated that the expression of BCL2A1 was induced by hypoxia, anoikis, serum starvation, and glucose deprivation, indicating that BCL2A1 was a common stress-inducible factor for the survival of ovarian cancer cells." (PMID 34572804, 2021). "We also noted that the induction of BCL2A1 expression coincided with the induction of HIF-1α at 2 h after hypoxia treatment, indicating that BCL2A1 may be an early response factor of hypoxia in ovarian cancer cells." (PMID 34572804, 2021). "Prolonged high expression of BCL2A1 reduced the cell proliferation rate by causing G1 arrested in ovarian cancer cells under a non-stressed culture condition." (PMID 34572804, 2021). "The results showed that the foci number of BCL2A1-expressing cells was increased by 1.4-fold (p = 0.01) in OVCA433 cells and 1.6-fold (p = 0.01) in A2780cp cells compared with that of the vector control cells, confirming that BCL2A1 enhanced the foci formation capacity of ovarian cancer cells." (PMID 34572804, 2021). "Moreover, to study the role of BCL2A1 in omental metastases of ovarian cancer cells, an ex vivo omental tumor-seeding model was used." (PMID 34572804, 2021). "Taken together, these results indicate that BCL2A1 could enhance the tumor colonization ability of ovarian cancer cells in omental metastasis." (PMID 34572804, 2021). "The results showed that a higher expression level of BCL2A1 was observed in all cancerous tissues compared with normal tissues and was positively correlated with high-grade and advanced ovarian cancers compared with the level of BCL2A1 in low-grade and early-stage ovarian cancers." (PMID 34572804, 2021). "To further investigate whether upregulated BCL2A1 is associated with metastatic ovarian cancers, we first examined the expression of BCL2A1 in clinical ovarian cancer tissues or cells obtained from the primary ovaries, ascites, and lavage of ovarian cancer patients by Western blot analysis." (PMID 34572804, 2021). "Based on the discrepancy in the mRNA and protein levels of BCL2A1 in ovarian cancer cells after various stressful challenges, it was hypothesized that the induction of the BCL2A1 protein by stressors might also involve posttranscriptional modifications, such as ubiquitin-proteasome degradation." (PMID 34572804, 2021). "Importantly, the subcellular localization of BCL2A1 to mitochondria further confirmed that BCL2A1 is a crucial regulator of the mitochondria-mediated apoptotic pathway, indicating that it is a potential therapeutic target for the treatment of the peritoneal metastases of ovarian cancer." (PMID 34572804, 2021). "Here, we report that BCL2A1, a BCL2 family member, acts as a hypoxia-inducible gene for promoting tumor progression in ovarian cancer peritoneal metastases." (PMID 34572804, 2021).
ovarian carcinoma (continued). "Our findings in this study showed that BCL2A1, which is induced by NF-κB signaling under various conditions of physiological stress, could enhance the cell proliferation, cell migration/invasion, and tumor growth of ovarian cancer cells using in vitro, ex vivo, and in vivo tumorigenic models." (PMID 34572804, 2021). "On the other hand, it is of interest to examine BCL2A1 in ovarian cancer cells in a non-stressed culture." (PMID 34572804, 2021). "Under stress conditions, BCL2A1 accumulated and colocalized with mitochondria to suppress intrinsic cell apoptosis by interacting with the BH3-only subfamily BCL2 members HRK/BAD/BID in ovarian cancer cells." (PMID 34572804, 2021). "This study showed that BCL2A1 interacts with neither BAX nor BAK in ovarian cancer cells, consistent with other studies." (PMID 34572804, 2021). "To verify whether other physiological stresses can induce BCL2A1, we subjected cultured OVCA433, A2780cp, and SKOV3 ovarian cancer cell lines to serum starvation, ultra-low attachment plates (anoikis assay), and glucose-free media." (PMID 34572804, 2021). "Our recent finding identified that BCL2A1, an inducible BCL2 member, not only protects cancer cells against cellular stress-mediated intrinsic (mitochondrial) apoptosis but also promotes tumor growth and metastatic progression in ovarian cancer peritoneal metastases." (PMID 35743298, 2022). "Indeed, HIF-1α had no obvious effect on BCL2A1 expression in ovarian cancer cells under hypoxic conditions, suggesting that BCL2A1 induction by hypoxia occurs in a HIF-1α-independent manner." (PMID 34572804, 2021). "However, ovarian cancer cells in which BCL2A1 was depleted did not retain cytochrome c in mitochondria, and all cytochrome c was released to the cytosol, supporting the notion that BCL2A1 suppresses intrinsic cell apoptosis under stress conditions." (PMID 34572804, 2021). "Furthermore, using CRISPR/Cas9-mediated HIF-1α gene knockout and co-treatment of CoCl2-simulated hypoxia in ovarian cancer cells, OVCA433 and ES-2, the changes of HIF-1α also did not alter the protein expression level of BCL2A1." (PMID 34572804, 2021).
triple-negative breast carcinoma (4 papers, 2018 to 2024). An invasive breast carcinoma which is negative for expression of estrogen receptor (ER), progesterone receptor (PR), and human epidermal growth factor receptor 2 (HER2). "It was shown that BCL2A1 silencing enhanced the therapeutic effect of triple-negative breast cancer cells on the Canady Helios Cold Plasma." (PMID 39834939, 2024). "Based on our discovery a combination of CHCP and anti-BCL2A1 treatment would be beneficial and a novel therapeutic treatment option for triple negative breast cancer and other cancers." (PMID 35260587, 2022). "In addition, the downregulation of BCL2A1 inhibits cell proliferation and metastasis in triple-negative breast cancer by reducing the phosphorylation of ERK1/2 and the expression of c-Myc via the MAPK pathway." (PMID 33391539, 2021).
atherosclerosis (3 papers, 2015 to 2021). A disease characterized by the build-up of fatty material and calcium deposition in the arterial wall resulting in partial or complete occlusion of the arterial lumen. "In rat atherosclerosis PCR array, Abca1, Bax, Bcl2, Bcl2a1, Cd44, Fabp3, Hbegf, Lypla1, Ptgs1, Selplg, Tgfb2, Tnc, and Vegfa had reverse trend between WT and MU groups, while the trends of Bcl2l1, Bid, Birc3, Cxcl1, Fas, Fn1, Itga2, Itga5, Lif, Nfkb1, Nr1h3, Ppard, and Sod1 were consistent." (PMID 34545275, 2021).
breast tumor (3 papers, 2015 to 2023). "Furthermore, it was also shown that MCPIP1 functions as a potent tumor suppressor and induces apoptosis of breast tumor cells by selectively enhancing mRNA decay of antiapoptotic gene transcripts, including Bcl2L1, Bcl2A1, RelB, Birc3, and Bcl3." (PMID 28197812, 2017).
fibrosarcoma (3 papers, 2022 to 2025). A malignant mesenchymal fibroblastic neoplasm affecting the soft tissue and bone. "In fibrosarcoma cells for example, BCL2A1 was rapidly induced after TNF-α stimulation." (PMID 35260587, 2022).
glioblastoma (3 papers, 2016 to 2018). The most malignant astrocytic tumor (WHO grade IV). "Prominent biomarkers of mesenchymal glioblastoma cells in neurosphere culture included CD44, BCL2A1, and LYN46–48." (PMID 29445239, 2018).
glioma (3 papers, 2013 to 2023). A benign or malignant brain and spinal cord tumor that arises from glial cells (astrocytes, oligodendrocytes, ependymal cells). "The results showed that BCL2A1 was significantly associated with mononuclear/macrophage infiltration in glioma." (PMID 37889551, 2023). "We found that 15 of 17 glioma single-cell sequencing datasets showed that BCL2A1 expression was mainly associated with the infiltration of macrophages and monocytes in the TISCH 2.0 database." (PMID 37889551, 2023). "Therefore, we speculate that BCL2A1 is closely associated with tumor-associated macrophage infiltration in gliomas." (PMID 37889551, 2023). "For the first time, we found that the expression of BCL2A1 was higher in human glioma tissues than in normal brain tissues (NBTs) in both public datasets and an in-house cohort." (PMID 37889551, 2023). "The results confirmed that glioma patients with high BCL2A1 expression had significantly shorter overall survival than glioma patients with low BCL2A1 expression." (PMID 37889551, 2023). "Correlation between BCL2A1 and clinicopathological characteristics in patients with gliomas in in-house cohort." (PMID 37889551, 2023). "Glioma was classified as grades II-IV according to the degree of malignancy, and public TCGA, CGGA, Rembrandt and Gravdendeel datasets indicated that BCL2A1 expression increased with increasing glioma grade." (PMID 37889551, 2023). "To investigate the biological function of BCL2A1 in gliomas, we screened 14 downregulated genes and 510 upregulated genes between the high and low BCL2A1 expression groups in TCGA-GBMLGG." (PMID 37889551, 2023). "We found that the expression of BCL2A1 is closely related to immune, stromal, and ESTIMATE scores, suggesting that BCL2A1 plays an important role in the immune microenvironment of glioma." (PMID 37889551, 2023). "IHC of an in-house cohort consisting of 10 NBTs and 174 glioma samples also confirmed that BCL2A1 had a higher expression level in glioma tissues." (PMID 37889551, 2023). "In summary, these data demonstrated that BCL2A1 was an independent predictor of response to TMZ chemotherapy in gliomas." (PMID 37889551, 2023). "Correlation between BCL2A1 and clinicopathological characteristics in patients with gliomas in TCGA." (PMID 37889551, 2023). "Then, we performed IHC staining analysis for CD68 and CCL2 in an in-house cohort, and the results showed that high BCL2A1 expression was significantly associated with CD68 and CCL2 expression in gliomas." (PMID 37889551, 2023). "Our study found that glioma patients with high BCL2A1 expression had poor responses to TMZ treatment." (PMID 37889551, 2023). "In this study, we explored the expression of BCL2A1 in gliomas and its relationship with glioma malignancy using public datasets and an in-house cohort." (PMID 37889551, 2023). "High BCL2A1 expression was associated with advanced WHO grade, IDH 1/2 wild type and the mesenchymal (ME) subtype, and its overexpression in glioma predicted resistance to temozolomide (TMZ) chemotherapy and unfavorable prognosis." (PMID 37889551, 2023). "Analysis of BCL2A1 in the Oncomine database showed that BCL2A1 expression was higher in brain and CNS cancer tissues than in normal tissues." (PMID 37889551, 2023). "BCL2A1 may be used as a supplementary marker to predict the response of glioma patients to TMZ chemotherapy." (PMID 37889551, 2023). "In addition, single-cell sequencing data from the TISCH2.0 database were used to further investigate the relationship between BCL2A1 and immune infiltration in gliomas." (PMID 37889551, 2023). "This may suggest that BCL2A1 promotes the progression of glioma and influences the prognosis of patients by participating in TAMs infiltration." (PMID 37889551, 2023). "As we hypothesized, high expression of BCL2A1 reduced survival time in all glioma patients, including LGG and GBM." (PMID 37889551, 2023). "The results demonstrated that BCL2A1 expression was higher in gliomas than in NBTs." (PMID 37889551, 2023).
glioma (continued). "We also systematically and comprehensively evaluated the prognostic value of BCL2A1 in glioma." (PMID 37889551, 2023). "In addition, BCL2A1 has been identified as a biomarker for postoperative seizure control in patients with low-grade glioma (LGG, WHO grade II–III)." (PMID 37889551, 2023). "Moreover, overexpression of BCL2A1 was closely related to TAM infiltration in the glioma immune microenvironment." (PMID 37889551, 2023). "Therefore, we utilized the TIMER 2.0 dataset to evaluate the correlation between BCL2A1 expression and immune cell infiltration levels in glioma." (PMID 37889551, 2023). "In addition, we used TCGA, Gill, Rembrandt and Gravendeel datasets to further investigate the BCL2A1 expression pattern in human gliomas." (PMID 37889551, 2023). "In conclusion, these findings suggest that BCL2A1 could serve as a promising prognostic indicator and immunotherapy target in gliomas." (PMID 37889551, 2023). "However, the OG cells abundantly express the mesenchymal markers CD44, BCL2A1, Wilms Tumor 1, similar to the recently described transitional glioma phenotype." (PMID 24278309, 2013). "However, the expression pattern and potential biological function of BCL2A1 in glioma remain unknown." (PMID 37889551, 2023). "Therefore, we speculate that BCL2A1 may promote the resistance of glioma to TMZ chemotherapy by regulating the infiltration of TAMs in the immune tumor microenvironment." (PMID 37889551, 2023). "Therefore, we speculated that BCL2A1 might accelerate tumor progression by promoting TAM infiltration in the glioma tumor microenvironment." (PMID 37889551, 2023). "In this study, we found that the expression of BCL2A1 in glioma was significantly higher than that in NBTs at both the mRNA and protein levels according to a comprehensive analysis of public databases and an in-house cohort that included 10 NBTs and 174 glioma samples." (PMID 37889551, 2023). "However, the expression pattern and potential biological function of BCL2A1 in gliomas are still unknown." (PMID 37889551, 2023). "Therefore, we investigated whether BCL2A1 affects resistance to TMZ chemotherapy in gliomas." (PMID 37889551, 2023). "For glioma patients treated with TMZ alone, BCL2A1 expression accurately predicted the survival of GBM and LGG patients." (PMID 37889551, 2023). "In summary, our results suggested that BCL2A1 was an independent prognostic marker and potential predictor of sensitivity to TMZ chemotherapy in glioma patients." (PMID 37889551, 2023). "However, the expression pattern and potential biological role of BCL2A1 in glioma remain unknown." (PMID 37889551, 2023). "To further validate our findings, we performed IHC and multiple immunofluorescences staining on two of the TAM markers and found that the expression of BCL2A1 was significantly correlated with CCL2 and CD68, and they were coexpressed in gliomas." (PMID 37889551, 2023). "Moreover, multiple fluorescence staining showed that BCL2A1, CD68 and CCL2 were coexpressed in glioma tissues." (PMID 37889551, 2023). "Moreover, the expression of BCL2A1 is correlated with the WHO grade and malignancy of glioma, and its high expression reduces the survival time of patients with LGG and GBM." (PMID 37889551, 2023). "Therefore, we speculate that BCL2A1 may promote TAM infiltration in glioma by influencing chemokines, including CCL2, and affect the tumor microenvironment and tumor progression in glioma." (PMID 37889551, 2023). "However, BCL2A1 expression did not accurately predict the survival of glioma patients with unmethylated MGMT promoters." (PMID 37889551, 2023). "However, for glioma patients who received only radiotherapy (IR), the expression of BCL2A1 did not affect their prognosis." (PMID 37889551, 2023).
periodontitis (3 papers, 2015 to 2025). An acute or chronic inflammatory process that affects the tissues that surround and support the teeth. "However, the functional roles of AQP9 and BCL2A1 in periodontitis remain poorly understood, and further studies are needed to clarify their specific contributions to disease progression." (PMID 41009952, 2025). "Therefore, research regarding the multiple layers of regulatory mechanisms including mRNA expression and alternative splicing of BCL2A1 are required to fully understand the role of this gene during the pathogenesis of periodontitis." (PMID 27531006, 2016). "Interestingly, recent discovery showed that BCL2A1 was increased not only in periodontitis but also in systemic diseases such as cardiovascular diseases and ulcerative colitis." (PMID 27531006, 2016). "Similarly, the skipping of exon 2 in BCL2A1 was predominant in periodontitis tissues (9/10), compared with healthy tissues (2/8)." (PMID 27531006, 2016). "Meanwhile, four genes, including FPR1, AQP9, BCL2A1, and VNN2 showed significantly higher expression in periodontitis patients and were strongly correlated with neutrophil infiltration, emerging as central to diagnosis and understanding of periodontitis." (PMID 41009952, 2025).
anaplastic large cell lymphoma (2 papers, 2022 to 2023). Anaplastic large cell lymphoma (ALCL) is a rare and aggressive peripheral T-cell non-Hodgkin lymphoma, belonging to the group of CD30-positive lymphoproliferative disorders, which affects lymph nodes and extranodal sites. "It was found that CEBPB and BCL2A1 can induce cell transformation and increase the survival of anaplastic large cell lymphomas cells." (PMID 37626099, 2023). "BCL2A1 overexpression was also found in many other non-Hodgkin's lymphomas such as mantle cell lymphoma and anaplastic large cell lymphoma (ALCL)." (PMID 35900226, 2022).
B cell lymphoma (2 papers, 2013 to 2022). "Bcl-2-related protein A1 (BCL2A1), discovered in 1995 in B cell lymphoma, is another pro-survival member preferentially expressed in lymphoid cells." (PMID 23441221, 2013).
cervical carcinoma (2 papers, 2021 to 2025). A carcinoma arising from either the exocervical squamous epithelium or the endocervical glandular epithelium. "BCL2A1 was induced by NF-κB signaling after TNF-α treatment in cervical cancer cells." (PMID 34572804, 2021).
chorioamnionitis (2 papers, 2019 to 2024). A morphologic finding indicating inflammation of the fetal sac membranes. "The intensity of BCL2A1 expression increases according to the stage progressionstage progression of acute histologic chorioamnionitis in the extra-placental membranes of spontaneous preterm birth." (PMID 39768244, 2024).
diabetes (2 papers, 2007 to 2023). "Besides, hypertension and diabetes are linked by CXCL8, HLA-B, and KANSL1; diabetes and obesity are linked by TRIM26 and MMP8; hypertension and obesity are linked by PLA2G7, FSTL3, STC2, and BCL2A1." (PMID 36685671, 2023).
ischemia (2 papers, 2010 to 2025). A hypoperfusion of the BLOOD through an organ or tissue caused by a PATHOLOGIC CONSTRICTION or obstruction of its BLOOD VESSELS, or an absence of BLOOD CIRCULATION. "Reperfusion injury of skeletal or cardiac muscle was markedly reduced by intraperitoneal or subcutaneous injection of recombinant human (rh)BCL2 protein or rhBCL2-related protein A1 (BCL2A1) (50 ng/g) given prior to ischemia or at the time of reperfusion." (PMID 20161703, 2010).
metastatic melanoma (2 papers, 2008 to 2021). A melanoma that has spread from its primary site to another anatomic site. "In contrast, the metastatic melanomas express higher levels of genes such as MAGE, GPR19, BCL2A1, MMP14, SOX5, BUB1, RGS20, and more." (PMID 18442402, 2008).